CYP19A1 (cytochrome P450 family 19 subfamily A member 1)
Diseases named in the same sentence as CYP19A1 in open-access papers (continued):
Sharing a sentence is not in itself a finding about the gene and the disease.
Gynecomastia (3 papers, 2014 to 2022). Abnormal development of large mammary glands in males resulting in breast enlargement. "Also, gynecomastia in adult males may appear due to high levels of oestrogens, resulting from the conversion of testosterone and androstendione by the HSD17B5 and CYP19A1 enzymes." (PMID 36140569, 2022).
hypothyroidism (3 papers, 2010 to 2023). Abnormally low levels of thyroid hormone. "As a matter of fact, hypothyroidism has been reported to induce Cyp19a1 mRNA levels in rat ovaries following the PTU treatment." (PMID 36769379, 2023).
ischemia (3 papers, 2019 to 2023). A hypoperfusion of the BLOOD through an organ or tissue caused by a PATHOLOGIC CONSTRICTION or obstruction of its BLOOD VESSELS, or an absence of BLOOD CIRCULATION. "However, DIM did not affect ERα/CYP19A1 signaling in mouse neurons subjected to OGD, which points to ERα-independent mechanisms of neuroprotective action of DIM against ischemia." (PMID 30778709, 2019).
leiomyoma (3 papers, 2009 to 2023). A well-circumscribed benign smooth muscle neoplasm characterized by the presence of spindle cells with cigar-shaped nuclei, interlacing fascicles, and a whorled pattern. "The enzyme aromatase, which is encoded by the CYP19A1 gene produces estrogens, appears to be an important regulator of estrogen response in leiomyomas." (PMID 22570742, 2012).
lung adenocarcinoma (3 papers, 2016 to 2022). A carcinoma that arises from the lung and is characterized by the presence of malignant glandular epithelial cells. "Previously, CYP19A1 rs3764221 has been studied to be significantly associated with the multicentric development of lung adenocarcinomas." (PMID 36527059, 2022). "Similar data, although restricted to women only, were confirmed in an independent study on 150 primary lung adenocarcinoma specimens, where CYP19A1 was found as the main driver of local estrogen supply." (PMID 30283331, 2018). "A previous study has shown that SNP rs3764221 is significantly correlated with CYP19A1 expression in non-cancerous lung tissues and affects the susceptibility to lung adenocarcinoma." (PMID 36527059, 2022). "Another study on 110 lung adenocarcinoma specimens found an association between CYP19A1 mRNA (RT-qPCR) and poor prognosis in females, never-smokers and harboring EGFR mutations." (PMID 30283331, 2018).
Arthralgia (2 papers, 2016 to 2021). "A cross-sectional study of patients receiving AIs found that women carrying at least one 8-repeat allele of the tetranucleotide repeat polymorphism of CYP19A1, associated with higher estrogen concentrations, had lower odds of AI-associated arthralgia." (PMID 27825388, 2016).
Asperger syndrome (2 papers, 2013 to 2021). "A case–control association analysis of individuals with Asperger syndrome (n = 174) revealed regions in 14 genes, including CYP19A1, that showed a nominally significant association with Asperger syndrome." (PMID 23697635, 2013).
bladder cancer (2 papers, 2011 to 2023). "In this study, we established the GMII consisting of eight glutamine metabolism-related genes (ENPP1, GALK1, TALDO1, CYP19A1, FASN, AHCY, SLC7A9, and HSPG2), a high value of which is associated with poor prognosis in bladder cancer patients." (PMID 36911676, 2023). "The expression of five of the eight GMII genes (TALDO1, AHCY, FASN, GALK1 and SLC7A9) in bladder cancer tissues was higher than that in normal tissues, while ENPP1, CYP19A1 and HSPG2 were down-regulated in tumor tissues (p < 0.05)." (PMID 36911676, 2023).
cervical carcinoma (2 papers, 2022 to 2024). A carcinoma arising from either the exocervical squamous epithelium or the endocervical glandular epithelium. "The expression levels of lnc-CCDC170–4:1, ESR, lncRNA SRA, and CYP19A1 were validated using qRT-PCR in 26 cases of cervical cancer tissue and 30 cases of normal cervical tissue." (PMID 39206151, 2024). "The relative expression level of lncRNA SRA and CYP19A1 mRNA were significantly higher in cervical cancer tissue." (PMID 39206151, 2024). "In conclusion, the expression of lncRNA SRA and CYP19A1 is elevated in cervical cancer, while lnc-CCDC170–4:1 and ESR1 expression is decreased in cervical cancer." (PMID 39206151, 2024). "The expressions of lnc-CCDC170–4:1, ESR1, lncRNA SRA, and CYP19A1 were validated in 26 cases of cervical cancer tissue and 30 cases of normal cervical tissue using qRT-PCR." (PMID 39206151, 2024). "In this study, we carried out qRT-PCR to evaluate the lncRNA SRA expression and its corresponding mRNA, CYP19A1, in cervical cancer and control tissues." (PMID 39206151, 2024). "Additionally, we analyzed the relationship between the expression of lncRNA SRA and CYP19A1 and the clinical-pathological characteristics of 26 cervical cancer patients." (PMID 39206151, 2024). "We found a significant increase in lncRNA SRA expression in cervical cancer tissues compared to the control, while the expression of CYP19A1 did not significantly differ between the two groups." (PMID 39206151, 2024).
cervical squamous cell carcinoma (2 papers, 2024 to 2025). A squamous cell carcinoma arising from the cervical epithelium. "Another study that analyzed cervical squamous cell carcinoma tissue samples found that the expression level of CYP19A1 was upregulated and ESR1 was downregulated in cancer." (PMID 40565012, 2025). "The expression levels of CYP19A1 and lncRNA SRA were upregulated, while those of ESR1 and lnc-CCDC170–4:1 were downregulated in cervical squamous cell carcinoma tissue." (PMID 39206151, 2024).
chondrosarcoma (2 papers, 2011 to 2018). A malignant cartilaginous matrix-producing mesenchymal neoplasm arising from the bone and soft tissue. "In that study, ESR1 and CYP19A1 mRNA expression were demonstrated in a set of 23 conventional chondrosarcomas and 7 (primary) chondrosarcoma cultures." (PMID 22613849, 2011).
cystic ovaries (2 papers, 2022 to 2025). "We report biallelic variants in CYP19A1 with an atypical presentation consisting of virilization in the child (development of clitoromegaly and the formation of the urogenital sinus), an absence of ovarian cysts, and FSH and LH levels that increased after 5 years of age." (PMID 35432193, 2022).
estrogen resistance (2 papers, 2023 to 2024). "Congenital estrogen deficiency results from the deletion of the aromatase gene cytochrome P450 family 19 subfamily A member 1 (CYP19A1) or abnormal function of ERs (estrogen resistance)." (PMID 38752176, 2024). "Recent reports suggest impaired glycemic homeostasis was observed in men with estrogen resistance and mutation in ESR1 and CYP19A1." (PMID 38001940, 2023).
female infertility (2 papers, 2022 to 2023). Diminished or absent ability of a female to achieve conception. "A positive association with female infertility risk for carriers of the C allele in CYP19A1 and null genotypes in GTSM1 (OR 11.979; 95% CI (4.570–31.400; p < 0.001) or GSTT1 (OR 13.169; 95% CI (4.518–38.380; p < 0.001) was found." (PMID 37107315, 2023). "To explore if the pattern of GSTs and CYP19A1 genotypes could be associated with the risk of female infertility, we studied combinations of genotypes." (PMID 37107315, 2023). "When both GSTs are deleted, the risk of developing female infertility is significant, independently of the CYP19A1 genotype; when all the presumed high-risk genotypes are present, we found a significant association with female infertility risk (OR 47,914; 95% CI (14,051–163,393; p < 0.001)." (PMID 37107315, 2023). "As far as we know, these are the first published results regarding the potential role of CYP19A1 codon 39 polymorphism and its potential effect together with GSTM1 and GSTT1 in the development of female infertility." (PMID 37107315, 2023). "The combined analysis of CYP19A1, GSTM1, and GSTT1 polymorphisms showed an association with female infertility risk for carriers of GSTM1 and GSTT1 present genotype (OR 7.108; 95% CI (2.777–18.197; p < 0.001)." (PMID 37107315, 2023). "This case-control study was performed to assess the potential role of CYP19A1, GSTM1, and GSTT1 in modifying individual predisposition to female infertility." (PMID 37107315, 2023). "Grouping CYP19A1 and GSTM1 genotypes, female infertility susceptibility was altered until when GSTM1 was present, as well as for carriers of GSTM1 null plus CYP19A1 C allele." (PMID 37107315, 2023). "The combination of all presumed high-risk genotypes, CYP19A1 TC/CC, GSTM1 deletion, and GST11 deletion, refers to a statistically significant association with female infertility risk (OR 47.914; 95% CI (14.051–163.393; p < 0.001)." (PMID 37107315, 2023). "In the analysis of the combination of CYP19A1 and GSTT1 genotypes, independently of GSTT1 and CYP19A1 polymorphisms, a statistically significant association was found with the risk of developing female infertility." (PMID 37107315, 2023). "To validate this premise, we conducted a case-control study to assess the putative role of CYP19A1, GSTM1, and GSTT1 in the modulation of individual predisposition to female infertility." (PMID 37107315, 2023). "Additionally, when GSTM1 and GSTT1 are deleted, there is a significant association with the risk of female infertility; this risk is independent of the CYP19A1 genotype." (PMID 37107315, 2023).
glioma (2 papers, 2021 to 2023). A benign or malignant brain and spinal cord tumor that arises from glial cells (astrocytes, oligodendrocytes, ependymal cells). "Letrozole, an aromatase inhibitor, is being researched in preclinical models as a potential treatment for high-grade gliomas, because this cancer frequently expresses estrogen synthase aromatase (CYP19A1)." (PMID 37629533, 2023). "Based on the discovery that the estrogen synthase aromatase (CYP19A1) is abundantly expressed in high- grade gliomas, the aromatase inhibitor, letrozole is being investigated in pre-clinical models as a novel agent against this malignancy." (PMID 33798227, 2021).
Hyperglycemia (2 papers, 2022 to 2025). An increased concentration of glucose in the blood. "We conclude that hyperglycemia induces CYP19A1 suppression through RORA dissociation from the RORE element on the CYP19A1 promoter." (PMID 35027651, 2022). "The results showed that RORE mutation (M-183/RORE/HG) completely reversed hyperglycemia-mediated CYP19A1 suppression, indicating that hyperglycemia suppresses CYP19A1 through the RORE element (located at −183) on the CYP19A1 promoter." (PMID 35027651, 2022). "We evaluated the potential molecular mechanism for hyperglycemia-mediated CYP19A1 suppression." (PMID 35027651, 2022). "The related motif deletion constructs were then generated from CYP19A1 full-length reporter construct (pCYP19-2000) for reporter assay, and the results showed that hyperglycemia-induced reporter suppression disappeared in the RORE deletion construct (M-183/RORE)." (PMID 35027651, 2022). "In this study, we show that transient hyperglycemia-mediated oxidative stress suppresses the expression of RORA, CYP19A1, and SOD2; prenatal RORA deficiency mimics maternal diabetes-mediated ALB, and postnatal RORA manipulation in the amygdala modulates maternal diabetes-mediated ALB in offspring." (PMID 35027651, 2022). "Our results suggest that transient hyperglycemia triggers persistent RORA suppression during subsequent normoglycemia and that the expression of CYP19A1 and SOD2 is regulated by RORA." (PMID 35027651, 2022).
melanoma (2 papers, 2014 to 2019). A malignant, usually aggressive tumor composed of atypical, neoplastic melanocytes. "Amplification of the CYP19A1 gene (aromatase) was ~1%, ~0.5%, ~0.3%, ~0.2%, ~1.6%, 0%, and ~0.2% in breast, colorectal, melanoma, ovarian, pancreatic, prostate, and uterine endometrial cancers, respectively." (PMID 31060224, 2019).
osteosarcoma (2 papers, 2018 to 2024). A usually aggressive malignant bone-forming mesenchymal neoplasm, predominantly affecting adolescents and young adults. "We also revealed that loss of USP7 inhibited the E2 content and enzymes Cyp19a1 and Cyp11a1, which suggested that mTORC1 stabilized USP7 may positive regulate E2 synthesis in osteosarcoma." (PMID 38467635, 2024).
postmenopausal osteoporosis (2 papers, 2019 to 2025). Metabolic disorder associated with fractures of the femoral neck, vertebrae, and distal forearm. "Aromatase, known as cytochrome P450 19A1 (CYP19A1), is closely related to postmenopausal osteoporosis." (PMID 30641909, 2019). "Moreover, polymorphisms in estrogen metabolism-related genes, such as PDSS1, CYP19A1, CYP1A1, and CYP1B1, have been associated with varied efficacy of raloxifene, a selective estrogen receptor modulator frequently prescribed for postmenopausal osteoporosis." (PMID 40411668, 2025).
acne (1 paper, 2021). An inflammatory process of the sebaceous glands which is characterized by comedones, nodules, papules and/or pustules on the skin. "In addition, two CYP19A1 SNPs, rs2236722 and rs700518, were significantly associated with acne presentation and severity." (PMID 33849530, 2021).
asthenozoospermia (1 paper, 2017). "In contrast, Cyp19a1, a gene associated with asthenozoospermia, oligozoospermia and female fecundity, was less expressed in FL2 bucks." (PMID 29157197, 2017).
asthma (1 paper, 2018). "HTR2C, CYP1B1, CYP19A1, ESR1, ESR2, PDR, and AR are found to be interrelated to hormonal disorders; ABCC1, NQO1, TIMP1, ADRB2, and ALOX5 are associated with asthma." (PMID 29861771, 2018).
astrocytoma (1 paper, 2021). "In this case-control study, we mainly investigated the role of ST6GAL1 and CYP19A1 polymorphisms in the occurrence of astrocytoma." (PMID 33836687, 2021). "This study explored the correlations between ST6GAL1 and CYP19A1 gene polymorphisms and astrocytoma susceptibility and prognosis." (PMID 33836687, 2021). "The correlation between ST6GAL1 and CYP19A1 variants and astrocytoma risk was calculated using logistic regression." (PMID 33836687, 2021). "The results of Cox regression analysis showed that the CYP19A1-rs2239611 and -rs1042757 polymorphisms were significantly correlated with the prognosis of astrocytoma." (PMID 33836687, 2021). "In this study, we investigated the correlation between ST6GAL1 and CYP19A1 polymorphisms and the risk and prognosis of astrocytoma." (PMID 33836687, 2021). "In stratified analyses, CYP19A1-rs2255192 might be associated with a higher risk of astrocytoma among the low-grade subgroup under recessive (p = 0.034) and additive (p = 0.030) models." (PMID 33836687, 2021). "In the stratified analysis, CYP19A1-rs2255192 might be associated with a higher risk of astrocytoma among the low-grade subgroup." (PMID 33836687, 2021). "Our results showed that rs2255192 in the CYP19A1 gene significantly increased the risk of astrocytoma among the low-grade subgroup under the recessive model (OR = 3.05, 95% CI = 1.11–8.34, p = 0.034) and the additive model (OR = 1.53, 95% CI = 1.04–2.24, p = 0.03)." (PMID 33836687, 2021). "Our results suggest that ST6GAL1 and CYP19A1 genes may be a potential biomarker of genetic susceptibility and prognosis to astrocytoma in the Chinese Han population." (PMID 33836687, 2021). "Firstly, we just selected two SNPs of the ST6GAL1 and CYP19A1 genes associated with astrocytoma risk, and more SNPs in ST6GAL1 and CYP19A1 are needed to detect." (PMID 33836687, 2021). "In summary, our study provided evidence that ST6GAL1 and CYP19A1 genes contribute to the development of astrocytoma among Chinese Han people." (PMID 33836687, 2021). "Secondly, the molecular mechanism under which ST6GAL1 and CYP19A1 polymorphisms affect the risk and prognosis in astrocytoma is not elucidated." (PMID 33836687, 2021). "Therefore, we selected four polymorphic sites of ST6GAL1 and CYP19A1 3’UTR to explore their impact on the risk and prognosis of astrocytoma." (PMID 33836687, 2021). "This evidence led us to think that the CYP19A1 gene may be involved in the development of astrocytoma." (PMID 33836687, 2021). "Thus, we suggested that CYP19A1-rs4646 may be involved in the development and progression of astrocytoma." (PMID 33836687, 2021).
atypical ductal hyperplasia (1 paper, 2018). Atypical ductal hyperplasia is an atypical proliferative lesion that falls in between the continuum from normal hyperplasia to low grade ductal carcinoma in situ. "Steroidogenic enzymes such as 17beta-hydroxysteroid dehydrogenase 1 (HSD17B1) and aromatase (CYP19A1) are frequently overexpressed in atypical ductal hyperplasia (ADH), DCIS, and IBC." (PMID 30338425, 2018).
Breast hypertrophy (1 paper, 2022). The presence of hypertrophy of the breast. "In this study we examined the association of genetic variants of progesterone receptor (PGR) and aromatase (CYP19A1) genes with gigantomastia risk." (PMID 35160095, 2022). "The aim of this study was to identify genetic risk factors for breast hypertrophy among genes for aromatase (CYP19A1) and progesterone receptor (PGR), examining their single nucleotide polymorphisms (SNPs) (CYP19A1: rs749292 and rs7172156 and PGR: rs1042838)." (PMID 35160095, 2022). "However, our findings showed more frequent G allele in CYP19A1 (rs749292) in women with gigantomastia." (PMID 35160095, 2022). "However, allele G of aromatase rs749292 (CYP19A1) increased the risk of gigantomastia (the probability for the homozygous GG genotype was 60%), but not significantly (p = 0.09)." (PMID 35160095, 2022). "Allele A in rs7172156 CYP19A1 appeared to be significantly less frequent in our control sample (23.44%) than in the general European population (40.02%) (p = 0.0028), but its frequency in women with gigantomastia was similar to the populational (p = 0.269)." (PMID 35160095, 2022). "However, we observed that allele G in rs749292 (CYP19A1) increased the risk of gigantomastia." (PMID 35160095, 2022). "Our results showed that allele G in rs749292 (CYP19A1) increased the risk of gigantomastia, but not significantly (p = 0.09)." (PMID 35160095, 2022).
Cachexia (1 paper, 2024). Severe weight loss, wasting of muscle, loss of appetite, and general debility related to a chronic disease. "Based on these findings, we propose that ACT may exert its anti-cachexia effects through the regulation of inflammatory response and energy metabolism via multiple targets, including CYP3A4, CYP19A1, CYP2E1, TNF, BCL-2, RYR2, and ATP2A1." (PMID 39872045, 2024).
chronic obstructive pulmonary disease (1 paper, 2018). A chronic and progressive lung disorder characterized by the loss of elasticity of the bronchial tree and the air sacs, destruction of the air sacs wall, thickening of the bronchial wall, and mucous accumulation in the bronchial tree. "A recent study on specimens from 73 patients with chronic obstructive pulmonary disease (COPD) and 48 controls described an association between both CYP19A1 and 17βHSD1 with COPD." (PMID 30283331, 2018).
cyst (1 paper, 2025). A sac-like closed membranous structure that may be empty or contain fluid or amorphous material. "Bins with a CYP19A1+ activated granulosa identity (cluster g9) were detected in the large activated cyst-like follicles in the medulla, surrounded by CYP17A1+ theca cluster t2." (PMID 40858568, 2025).
diabetic retinopathy (1 paper, 2020). "The haplotype analysis was further conducted and the results indicated that Crs1062033Grs17601876Ars3751599 in CYP19A1 played a protective role (OR = 0.48, 95% CI = 0.25–0.91, P = 0.026) in T2DM patients with diabetic retinopathy." (PMID 32814585, 2020).
embryonal carcinoma (1 paper, 2025). A non-seminomatous malignant germ cell tumor characterized by the presence of large germ cells with abundant cytoplasm resembling epithelial cells, geographic necrosis, high mitotic activity, and pseudoglandular and pseudopapillary structures formation. "Expression of genes involved in general steroid biosynthesis (STAR, POMC, CYP11A1, FDX1) and the aromatase-coding gene CYP19A1 was the highest in embryonal carcinomas." (PMID 40011822, 2025).